IL1B (interleukin 1 beta)
Diseases named in the same sentence as IL1B in open-access papers (continued):
Sharing a sentence is not in itself a finding about the gene and the disease.
breast cancer (continued). "Furthermore, IL-1β stimulates γδT cells to express IL-17, resulting in the systemic expansion and polarization of neutrophils in mice with mammary tumors and endowing them with the ability to inhibit cytotoxic CD8+ T lymphocytes, thereby promoting tumor metastasis." (PMID 36497209, 2022). "It has also been reported in the 4T1 triple negative mouse breast cancer model that Gr1+ cells primarily promote the metastatic cascade by facilitating extravasation of malignant cells at the distant metastatic lungs through IL1β and matrix metalloproteinase secretion." (PMID 35309358, 2022). "In addition, we have recently shown an immunomodulatory effect of this peptide, which significantly decreased the expression of IL-1β in tumor and lung tissues and increased the levels of IL-10 anti-inflammatory cytokines in the primary tumor of 4T1 mouse mammary carcinoma as observed in other AMPs." (PMID 35601827, 2022). "Moreover, co-culture of IL-1β-stimulated hUCMSCs with embelin-treated breast cancer cells could effectively induce apoptosis in breast cancer cells." (PMID 34282169, 2021). "This rationale is also strengthened by results from preclinical models, in which combination of anti-IL-1β blocking antibodies with programmed cell death protein 1 (PD-1) blockade exhibited significantly improved tumor control and overall survival of mice in murine breast cancer models." (PMID 33530653, 2021). "It has reported that IL-1β inflammatory response could inhibit breast cancer cell metastasis." (PMID 34789197, 2021). "The results showed that the secretion of TNF-α, IL-6 and IL-1β were all decreased after AT-I treatment, and we concluded that AT-I could suppress tumorigenesis in breast cancer via inhibiting TLR4/NF-κB pathway, and down-regulate downstream pro-inflammatory cytokines." (PMID 33363472, 2020). "Furthermore, IL1β treatment could induce icd‐IL1R2 release in a time‐ and dose‐dependent manner in IL1R2‐overexpressing breast cancer cells, and IL1R2 neutralizing antibody pretreatment reversed IL1β induced BMI1 upregulation in breast cancer cells." (PMID 31921558, 2020). "Thus, we investigated whether the ATP-enhanced inflammasome components are involved in IL-1β secretion and consequently related to tumor progression, including invasion and angiogenesis, in both breast cancer cells, and whether the effects are P2Y2R-dependent." (PMID 32397236, 2020). "Therefore, we hypothesized that the increased inflammasome components take part in the malignancy of RT-R breast cancer cells by mediating the release of mature IL-1β." (PMID 32397236, 2020). "Thus, ATP released from both breast cancer cells during the incubation time (24 h) to detect IL-1β and VEGF production could activate P2Y2R to induce IL-1β and VEGF-A production without the addition of exogenous ATP." (PMID 32397236, 2020). "In contrast with the previous study showed that rottlerin enhances IL-1β-induced COX-2 expression through sustained p38 MAPK activation in MDA-MB-231 human breast cancer cells, these differences suggest that the nature of its effects may vary in a stimuli-dependent or cell-type-specific manner." (PMID 32505192, 2020). "A mechanistic insight between IL-1β, inflammation and cancer was recently provided by Wellenstein and coworkers by showing that IL-1β is responsible for neutrophil expansion and neutrophilic inflammation that potentiates the metastatic progression of breast cancer." (PMID 33194755, 2020). "As IL-1β may contribute to breast cancer development and metastasis and may regulate the migratory phenotype of TNBC cells through HIF-1α, we sought to evaluate whether IL-1β could be involved in the activation of a hypoxia-related gene signature in TNBC patients." (PMID 32778144, 2020).
breast cancer (continued). "Notably, analysis of pro-inflammatory genes that were upregulated in mammary CAFs using the STRING database of human protein networks, showed enrichment of inflammatory pathways, including NLRP3/IL-1β signalling, confirming the functional connectivity between genes of this pathway in breast cancer." (PMID 31558756, 2019). "Moreover, IL-1β induces ICI-EMT in a 6D breast cancer cell model by activating the IL-1β/IL–1R1/β-catenin pathway and up-regulating Twist1, leading to ESR1 gene promoter methylation, and to methylation-dependent down-regulation of ERα receptor, linked to tamoxifen resistance." (PMID 31557902, 2019). "Blood monocytes, tissue macrophages, and other cells generate and release interleukin-1β (IL-1β) into the extracellular environment, which has pro-inflammatory effects and participates in the proliferation, invasion, metastasis, and angiogenesis of breast cancer." (PMID 31500658, 2019). "Nevertheless, taken together with recent reports that the effect of targeting CAFs may depend on tumour type and on the experimental systems that were used, future studies should be performed to carefully examine the benefit of targeting CAF-derived IL-1β in breast cancer." (PMID 31558756, 2019). "Hence, IL-R1 signalling could have both pro- and anti-tumour functions and it is possible that IL-1A and IL-1B may exert opposite functions in breast cancer progression." (PMID 29760166, 2018). "Taken together with our finding that IL1B, IL1R1 gene three SNP are also associated with the risk for the disease, we suggest that inflammation via innate and adaptive immunity contributes to multifactorial hereditary predisposition to pathogenesis of the breast cancer." (PMID 29719585, 2018). "Here, we identified the impact of TNF-α and IL-1β on the inflammatory phenotype of CAFs and MSCs by determining the expression of inflammatory chemokines that are well-characterized as pro-tumorigenic in breast cancer: CCL2 (MCP-1), CXCL8 (IL-8) and CCL5 (RANTES)." (PMID 25928089, 2015). "In aggressive human and murine breast cancer cells, a biologically active 20-kDa peptide from the N-terminal domain of a2V (a2NTD) is proteolytically cleaved, secreted in the microvesicles and stimulates human peripheral blood mononuclear cells to produce IL-1β and IL-10." (PMID 26460736, 2015). "In addition, high levels of serum IL-1β correlate with recurrence in breast cancer patients." (PMID 26106384, 2015). "Finally, IL-1β may also be involved in premalignant breast cancer based on studies that showing increased IL-1β expression in pre-invasive DCIS." (PMID 26106384, 2015). "Interestingly, monocytes from patients with early breast cancer produced similar amounts of cytokines (IL-8, IL-6, IL-1β and TNF) as those observed in patients with advanced disease (LRR/MBC), suggesting that monocytes are functionally affected already early in the disease." (PMID 25992611, 2015). "Several studies have shown how IL-1β may contribute to breast cancer development and metastasis." (PMID 26696754, 2015). "However, given the relevance of the hypoxic microenvironment in tumor progression, we wondered how IL-1β might affect breast cancer cell migration under hypoxia." (PMID 26696754, 2015). "Furthermore, TNF-α, IL2, and IL1b have not been associated with fatigue and RT in breast cancer and other malignancies." (PMID 24800238, 2014). "The results from our study do not support the hypothesis that the cytokine polymorphisms studied [IL1A +4845G>T, IL1B -511C>T, IL1B +3954C>T, IL1RN +2018T>C, IL4R -1902A>G, IL6-174G>C and IL10-1082G>A] are associated with breast cancer susceptibility and severity." (PMID 16842617, 2006). "The adenoviral vector vaccine combined with IL‐1β induces the generation of pulmonary TRM cells, reducing lung metastases in breast cancer." (PMID 39802636, 2025).
breast cancer (continued). "In breast cancer models, CKI has been found to enhance the anti-tumor effects of chemotherapy by upregulating IL-1β and modulating immune-related pathways, further supporting its potential immunotherapeutic role." (PMID 40248100, 2025). "In breast cancer, MET signaling activates the MAPK pathway and promotes the release of inflammatory cytokines such as IL-1β, IL-8, and CXCL1, thereby reshaping the brain microenvironment and enhancing brain metastasis." (PMID 40860829, 2025). "This systematic review highlights consistent associations between increased pro-inflammatory cytokines (i.e., IL-6, IL-1β, TNF-α), reduced levels of hippocampal BDNF, and cognitive impairment in preclinical models of breast cancer and chemotherapy." (PMID 41155372, 2025). "In this study, treatment of MCF‐7 breast cancer cells with SL extract led to a significant, dose‐dependent increase in several key cytokines, including TNF‐α, TGF‐β, IL‐1β, DEF‐β, and IFN‐γ." (PMID 40685820, 2025). "Our findings demonstrate a significant upregulation of key pro-inflammatory cytokines such as IL-6, IL-1β, TNF-α, and IL-12 (p40) in the plasma of breast cancer patients, with expression correlating positively with tumor stage and grade." (PMID 40612845, 2025). "Leptin, a hormone mainly secreted by adipose tissue and involved in regulating body weight and pro-inflammatory response, can induce the expression of IL-1β, which upregulates downstream VEGF expression and signaling in breast cancer." (PMID 39858071, 2025). "They discovered a strong correlation between ox-LDL, IL-1β, and TNF-α and post-menopausal breast cancer." (PMID 40584290, 2025). "In breast cancer, CAFs-driven NLRP3 and IL-1β drive tumor growth and metastasis by orchestrating an immune-suppressive microenvironment." (PMID 41291696, 2025). "Pro‐inflammatory cytokines such as IL‐1β and TNF‐α further amplify this effect by stimulating both NF‐κB signaling, and ABCG2 expression in certain breast cancer cell lines, suggesting a coordinated response involved in drug resistance." (PMID 40654246, 2025). "We also extracted exosomes from two additional murine breast cancer cell lines (4T07 and EMT6) and found that exosomes from the ISO‐treated group prominently enhanced the neutrophils’ ability to secrete IL‐1β compared to exosomes from the control group." (PMID 39630109, 2025). "Conversely, in breast cancer, IL-1β facilitates the invasion, migration, and EMT of breast carcinoma cells." (PMID 40830103, 2025). "The murine breast cancer cell line EO771 was selected as a breast cancer model, since the growth of EO771 tumors is dependent on IL-1β derived from the intra-tumoral myeloid compartment." (PMID 39224600, 2024). "The pathways discussed and found to be consistently affected by the reported nutraceuticals in breast cancer-Nf-κB, TNF-α/IL-1β, PI3K/Akt, and MAPK/p38-are interconnected and offer the most relevant molecular targets for therapeutic protocols." (PMID 39728433, 2024). "When we exposed human macrophages to resistant breast cancer-derived EVs, we observed a pro-inflammatory profile with increased TNF-α, IL-1β, and IFN-γ expression, exhibiting anti-tumoral characteristics." (PMID 39474419, 2024). "Further research should examine the involvement of CST7 in the infiltration of immune cells in breast cancer tissues and analyze possible connections between CST7, IL1B, and ITGA5 in relation to breast cancer." (PMID 39552709, 2024). "It was demonstrated that women with advanced breast cancer frequently experience pain and have high systemic levels of TNF-α and IL-1β." (PMID 38940936, 2024). "Building upon our previous work showing that Notch primes IL1β expression in TNBC, these data provide mechanistic insight into how IL1β is further processed in this breast cancer subtype, leading to TAM recruitment, CTL exclusion, and tumor progression." (PMID 39353903, 2024).
breast cancer (continued). "IC50 concentrations were given to breast cancer co-culture models (MCF-7/THP-1 and MDA-MB-231/THP-1) planted and merged according to the procedure, and after 24 h using flow cytometry, IL-1β, IL-6 levels of IL-8, IL-10, and TNF-α were measured." (PMID 39175950, 2024). "Like IL-1β, IL-18 has both pro and antitumorigenic effects by regulating the TME in breast cancer as well." (PMID 36823153, 2023). "Breast cancer cells induce the expression of cytokines (CCL2, CCL5, IL-1β, and IL-6) and immunomodulators (COX2, HIF-1α, VEGFα, and PD-L1) by cancer-associated adipocytes." (PMID 36670988, 2023). "Finally, we present current trials evaluating IL-1β in breast cancer and other solid tumor malignancies and discuss future studies that may provide a strong scientific rationale for the combination of IL-1β and immunotherapy in the neoadjuvant and metastatic setting for people with TNBC." (PMID 37065483, 2023). "Fibroblast-derived IL-1β is secreted through NLRP3 inflammasomes, which are activated by various DAMPs including necrotic fluid from breast cancer cells." (PMID 36932407, 2023). "Breast cancer cells secrete IL-1β, in response to which astrocytes secrete HGF, which in turn increases IL-1β expression in breast cancer cells." (PMID 37108425, 2023). "MDSC-derived IL-1β induces IL-17 secretion by CD4+ T cells leading to curtailed anti-tumor effect of 5-FU against several kinds of tumors including lymphoma, breast cancer, melanoma, and lung cancer." (PMID 36932407, 2023). "TNF-α binds to TNFR in breast cancer cells and activates MAPK/ERK and NF-kB, and IL-1β secreted by adipocytes binds to IL-1R and upregulates and activates NF-kB and CREB via its receptor IL-1R." (PMID 37296983, 2023). "Docosahexaenoic acid (DHA) inhibits breast cancer, and when it is added to the breast cancer cell line MDA-MB-231, caspase-1 and GSDMD activities are enhanced, and pyroptosis occurs, which manifests as increased IL-1β secretion and membrane perforation." (PMID 36605484, 2023). "Therefore, regarding central role of IL-1β in growth and proliferation of breast cancer cells, our findings may be defined as a part of the mechanism of cytotoxicity by dandelion extract, ATRA, or the combination of both, on breast cancer cells, MCF-7, and MDA-MB231." (PMID 37700002, 2023). "IL-1β, IL-18 and ASC, the pivotal elements of the inflammatory signaling pathway, are upregulated in breast cancer cells, but the specific cancer-promoting mechanism of NLRP1 inflammasomes needs to be further verified." (PMID 37020871, 2023). "Some cytokines (leptin, IL-1β, IL-6, IL-8, IL-23, IL-17, TGF-β, IL-10) are mostly reported to stimulate while others (Il-2, IL-12, IFNs) inhibit breast cancer proliferation and/or invasion." (PMID 36835413, 2023). "Our study suggests that breast cancer patients with psychological distress have worse cognitive functioning based on MMSE and lower quality of life, with higher levels of IL‐1β, TNF‐α, and IL‐4." (PMID 36965094, 2023). "Exosomal miR‐183 derived from breast cancer cells elevates the levels of TNF‐α, IL‐6, and IL‐1β in macrophages." (PMID 36705422, 2023). "Hub genes are involved in the generation of cancer stem cells (CSCs) and are related to inflammatory mediators, including CXCL8, IL1-β and PTGS2, which promote inflammation and breast cancer growth, metastasis, and development." (PMID 37138170, 2023). "IL-1β also activates focal adhesion kinase and Src to induce MMP9 production and invasion of MCF-7 breast cancer cells." (PMID 36835413, 2023). "Compared with normal breast tissue, the expression of Nlrp3, caspase-1 and IL-1β genes in the NLRP3 inflammatory pathway was significantly upregulated in mouse and human mammary tumor stroma." (PMID 37020871, 2023). "CXCL8 plays a role in angiogenesis, and IL-1β enhances tumor inflammation, activates the β-catenin signaling pathway and induces EMT in breast cancer cells in addition to the expression of PTGS2." (PMID 37138170, 2023).
breast cancer (continued). "The results of Meng’s meta-analysis showed a significant reduction in IL-2, IFN-γ, IL-6, IL-1β, and TNF-α levels in breast cancer patients participating in the Qigong practice group." (PMID 36831519, 2023). "In breast cancer cells, the expression levels of NLRP3 and IL-1β are significantly higher compared to normal tissues, contributing to the occurrence of pyroptosis in the tumor microenvironment." (PMID 37542283, 2023). "Given the absence of IFN-γ expression in M1 polarized macrophages, we assessed the ability of IL-1β, which was robustly upregulated in M1 polarized cells, to increase PIGR expression in breast cancer cells." (PMID 36207349, 2022). "Using in vitro experiments and dataset analysis, the authors also demonstrated that through this pathway, IL-1β is related to lymphatic vessel proliferation, whereas NOD-like receptor protein 3 is related to breast cancer invasion and metastasis." (PMID 35844605, 2022). "The current results suggest TET-1 as responsible for the IL-1β-dependent tumor progression of the MCF-7 cell line, indicating its potential therapeutic treatment as a druggable target in breast cancer acting on progression and bone metastasis." (PMID 36499741, 2022). "IL-1β induces upregulation of baculoviral IAP repeat containing 3, which is involved in resistance to doxorubicin in breast cancer." (PMID 36264639, 2022). "Alternatively, long-term DEHP exposure can also induce upregulation of the inflammatory cytokines IL1α, IL1β, IL6, and GM-CSF through the MAPK/p38 signaling pathway to facilitate breast cancer progression." (PMID 35203627, 2022). "In conclusion, our data show that small molecule inhibitors of IL1β and Caspase-1, MLX01 and VX765, are attractive therapeutic strategies for preventing breast cancer-induced bone disease." (PMID 36230739, 2022). "For example, IL-1β promotes the proliferation, migration, angiogenesis, and release of HMGB1 in smooth muscle cells, while IL-18 promotes the migration of breast cancer cells by down-regulating claudin-12 and inducing the P38/MAPK pathway." (PMID 36233009, 2022). "Meanwhile, high expression of IL1β, IRAK1 and Caspase-1 is closely correlated with reduced overall survival and distant recurrence of breast cancer." (PMID 36230739, 2022). "The effect of increasing the concentration of IL-1β on PIGR expression and secretory component secretion in breast cancer cells was further investigated." (PMID 36207349, 2022). "The results showed that IL-1β, IL-8, and TNF-α expression levels in breast cancer tissues were elevated compared with those in the normal appearing tissues." (PMID 35188865, 2022). "Importantly, inhibiting Caspase-1 reduces bone metastasis without adversely affecting tumours outside of bone or immune cell regulation, suggesting that targeting immediately upstream of IL1β may be a good therapeutic strategy for treating patients with breast-cancer-induced bone disease." (PMID 36230739, 2022). "The expression of AGP and IL-1β, IL-8 and TNF-α in breast cancer tissues were significantly higher than those in normal appearing tissues." (PMID 35188865, 2022). "The expression levels of IL-1β, IL-8, and TNF-α increased with progression through the clinical stages of breast cancer, and the differences were statistically significant (P = 0.03)." (PMID 35188865, 2022). "The expression levels of IL-1β, IL-8, and TNF-α were significantly elevated in breast cancer tissues compared with that in normal appearing tissues." (PMID 35188865, 2022). "The expression of the IL-1-related genes, such as Il1B, CASP1 and IRAK1, have been identified to be significantly up-regulated in breast cancer compared with normal mammary tissue." (PMID 36230739, 2022). "On the other hand, NLRP3 and IL-1β expression in TAMs correlated with survival, lymph node invasion, and metastasis in patients with HER2+ breast cancer." (PMID 33840390, 2021).